RNF168 (ring finger protein 168)
Diseases named in the same sentence as RNF168 in open-access papers (continued):
Sharing a sentence is not in itself a finding about the gene and the disease.
breast carcinoma (continued). "We next examined a panel of human breast cancer cell lines for their RNF168 expression levels and their response to etoposide." (PMID 27558965, 2016). "RNF168 is highly expressed in breast cancer samples, compared with normal breast tissue." (PMID 29974997, 2018). "As modulation of ERɑ levels is one feasible approach to target oestrogen signalling and cell proliferation, RNF168 could be a potential drug target for ERɑ‐positive breast cancers." (PMID 29974997, 2018). "We first identify the localization of RNF168 in breast cancer cell line." (PMID 29974997, 2018). "Besides, we also observe the higher expression of RNF168 in breast cancers compared with normal tissue and the poor prognosis survival correlation with RNF168 expression in endocrine therapy patients." (PMID 29974997, 2018). "On the basis of these data, we propose that selective modulation of RNF168 expression or/and functional cooperation with ERɑ could be a strategy to inhibit ERɑ‐positive breast cancer proliferation." (PMID 29974997, 2018). "Chromatin immunoprecipitation revealed that ERɑ transcription is associated with RNF168 recruitment to ERɑ promoter region, suggesting that transcriptional regulation is one mechanism by which RNF168 regulates ERɑ mRNA level and ERɑ signalling in breast cancer cells." (PMID 29974997, 2018). "Of note, two of the studied mutations were also simultaneously identified in Helsinki: FANCD2 c.2715 + 1G > A in clinical panel sequencing of a patient with early onset triple-negative breast cancer and RNF168 c.640_644del5 in exome sequencing of hereditary breast cancer patients." (PMID 28386063, 2017). "To determine whether RNF168 expression level correlates with the response to etoposide, we examined the cytotoxic effect of etoposide on breast cancer cell lines that have different levels of endogenous RNF168." (PMID 27558965, 2016). "The high levels of RNF8 and low levels of RNF168 in steady-state untreated MCF-7 breast cancer cells may also explain the inability of RNF8 overexpression or its depletion to modulate FOXM1 expression." (PMID 27526106, 2016). "Notably, knock down of RNF168 in human breast cancer cell lines T47D and MDA-MB-231 promoted their resistance to etoposide-induced cytotoxicity." (PMID 27558965, 2016). "Additionally, the RNF168 level is higher in breast cancer tissues than in normal breast tissues." (PMID 39996778, 2025). "The estrogen receptor α (ERα), a key player in breast cancer development, is influenced by RNF168, which interacts with the promoter region of ERα to enhance its transcriptional activity, thereby boosting the ERα signaling cascade and promoting the proliferation of ERα-positive breast cancer cells." (PMID 39996778, 2025). "However, whether RNF168 can combine with other targets in breast cancer cells to affect the progress of breast cancer still needs further research." (PMID 36771081, 2023). "RNF168 could bind to Erα promoter region and facilitate ERα transcriptional activity, enhance the activity of the ERα signal pathway, and thus promote the proliferation of Erα-positive breast cancer cells." (PMID 36771081, 2023). "Previous studies have found that RNF168 expression is decreased in various BRCA1-mutant cancer cell lines and primary tumors, such as breast cancer and ovarian cancer." (PMID 36771081, 2023). "We also found evidence that RNF168, an E3 ubiquitin ligase able to ubiquitinate FOXM1 in breast cancer, displays nuclear localisation." (PMID 33981003, 2021). "To explore this possibility, we first overexpressed RNF168 and two other DDR-related E3-ligases, RNF4 and RNF8, in the MCF-7 breast carcinoma cells, and studied their effects on FOXM1 expression." (PMID 27526106, 2016). "Collectively, these data suggest that RNF168 cooperates with RNF8 to mediate the ubiquitination and degradation of SUMOylated FOXM1 in breast cancer genotoxic response." (PMID 27526106, 2016).
breast carcinoma (continued). "To confirm these findings in human cells, we performed similar fractionation experiments of breast cancer cell lines T47D and MDA-MB-231 and their RNF168-knockdown counterparts." (PMID 27558965, 2016). "The physiological relevance of RNF168-mediated FOXM1 repression is further emphasized by the significant inverse correlation between FOXM1 and RNF168 expression in breast cancer patient samples." (PMID 27526106, 2016). "The results showed that RNF168 interacted with FOXM1, suggesting that FOXM1 and RNF168 form complexes in breast cancer cells both in the absence and in the presence of epirubicin." (PMID 27526106, 2016). "RNF168 exhibited a higher level in breast cancers compared with normal breast tissue and correlates with a poor endocrine treatment outcome." (PMID 36771081, 2023). "Moreover, the phosphorylation levels of KDM1A were upregulated in breast cancer, UCEC, and LUAD, and the phosphorylation of KDM1A at S131 and S137 was experimentally supposed to play a role in regulating RNF168-dependent 53BP1 recruitment in response to DNA damage and resisting DNA damaging agents." (PMID 34925656, 2021).
ovarian carcinoma (4 papers, 2015 to 2024). A malignant neoplasm originating from the surface ovarian epithelium. "Western Blot assay showed that p62 was increased and RNF168 was decreased in ovarian cancer cells endogenously overexpressing LOC730101 compared to the control." (PMID 39695078, 2024). "Moreover, LOC730101 inhibits the expression and activity of RNF168 via p62, which in turn affects H2A ubiquitination-mediated DNA damage repair and promotes drug sensitivity in ovarian cancer cells." (PMID 39695078, 2024). "The results showed that the overexpression of LOC730101 significantly increased the expression of p62, and decreased the expression of RNF168 and H2AK119ub compared with the control group after the treatment of ovarian cancer cells with cisplatin and niraparib respectively." (PMID 39695078, 2024). "When p62 was transiently knocked down, p62 was decreased in both control and ovarian cancer cells overexpressing LOC730101, while the decreased RNF168 was reverted in ovarian cancer cells overexpressing LOC730101." (PMID 39695078, 2024). "Indeed, in ovarian cancer cell lines WRAP53β rapidly accumulates at DNA breaks, where it orchestrates the accumulation of DNA repair proteins involved in both HR and NHEJ, including RNF168, 53BP1, BRCA1 and RAD51." (PMID 26426684, 2015). "Furthermore, in ovarian cancer cell lines, WRAP53β was rapidly recruited to DNA double-strand breaks, where it orchestrated the recruitment of repair factors involved in homologous recombination and non-homologous end joining, including RNF168, 53BP1, BRCA1 and RAD51." (PMID 26426684, 2015).
esophageal cancer (3 papers, 2021 to 2024). A primary or metastatic malignant neoplasm involving the esophagus. "Mechanistic studies showed that RNF168 influenced the malignant behavior of esophageal cancer cells by regulating the Wnt/ β-catenin signaling pathway." (PMID 33493132, 2021). "Our results also show that RNF168 knockdown interferes with the proliferation and migration of esophageal cancer cells, and suppresses Wnt/β-catenin signaling." (PMID 33493132, 2021). "To further investigate the effects of RNF168 on the biological activity of esophageal cancer cells, we knocked down RNF168 expression in ECA-109 and EC9706 cells by lentiviral transduction." (PMID 33493132, 2021). "In this study, we also knocked down RNF168 expression to see how this influenced the malignant behavior of esophageal cancer cells, and found that proliferation was significantly inhibited." (PMID 33493132, 2021). "Knockdown of the RNF168 gene inhibited proliferation of esophageal cancer cells, promoted cell apoptosis, and interfered with cell movement, ultimately inhibiting tumor xenograft growth." (PMID 33493132, 2021). "Furthermore, elevated levels of ring finger protein 168 were reported to contribute to malignant cell proliferation and invasion in esophageal cancer." (PMID 38273295, 2024). "Therefore, RNF168 may participate in the Wnt/β-catenin signaling pathway and thus modulate the proliferation and apoptosis of esophageal cancer cells." (PMID 36771081, 2023). "However, the role of RNF168 in the pathogenesis of esophageal cancer is still unclear." (PMID 36771081, 2023). "Hence, it was concluded that RNF168 may participate in the regulation of classic Wnt/β-catenin signaling in esophageal cancer." (PMID 33493132, 2021). "For example, it needs further research on how RNF168 reduces the polyubiquitination of STAT1 and how it affects the protein of the Wnt/β-catenin signaling pathway to promote the progression of esophageal cancer." (PMID 36771081, 2023). "To further explore how RNF168 contributes to ESCC, we searched the TCGA database, and analyzed 20,140 background genes in 184 cases of esophageal cancer with the LinkedOmics online data analysis tool." (PMID 33493132, 2021). "Heatmaps showed the relationship between RNF168 and WNT3A expression and survival in 184 patients with esophageal cancer." (PMID 33493132, 2021). "Ring finger protein 168 repressed STAT1 polyubiquitination and degradation to upregulate JAK-STAT1 signaling and the downstream functional genes, contributing to the growth and invasion of esophageal cancer." (PMID 38273295, 2024). "RNF168 may stabilize STAT1 protein, which is a core component of the JAK-STAT signaling pathway, by inhibiting the polyubiquitination of STAT1, and thus promote the proliferation and invasion of esophageal cancer cells by activating the JAK-STAT signaling pathway." (PMID 36771081, 2023).
esophageal squamous cell carcinoma (3 papers, 2021 to 2023). Esophageal squamous cell carcinoma (ESCC) is a type of esophageal carcinoma (EC) that can affect any part of the esophagus, but is usually located in the upper or middle third. "Here we report that expression of RNF168 in esophageal squamous cell carcinoma is increased with respect to normal esophageal epithelial tissue." (PMID 33493132, 2021). "The relationship between pathological staging and RNF168 expression in esophageal squamous cell carcinoma samples was analyzed using the TCGA database, and the results showed that expression of RNF168 in STAGE II was higher than in other stages." (PMID 33493132, 2021). "A Western blot was performed to verify that silencing RNF168 activated the expression of ATM in esophageal squamous cell carcinoma cells." (PMID 33493132, 2021). "RNF168 expression was also increased in esophageal squamous cell carcinoma (ESCC) compared with normal esophageal epithelium and related to tumor stage and depth of invasion." (PMID 36771081, 2023). "Recent studies have shown that in esophageal squamous cell carcinoma (ESCC), the expression of RNF168 was increased, which enhances tumor growth." (PMID 37176148, 2023). "It was found that RNF168 and WNT3A mRNA levels were negatively correlated with the survival rate (overall survival and disease-specific survival) of patients with esophageal squamous cell carcinoma." (PMID 33493132, 2021). "However, the role of RNF168 in the development of esophageal squamous cell carcinoma (ESCC) has not been fully elucidated." (PMID 33493132, 2021).
prostate carcinoma (3 papers, 2021 to 2024). A carcinoma that arises from epithelial cells of the prostate gland. "In autophagy-deficient prostate cancer cells, USP14 acts as a regulator of DNA damage response by negatively regulating RNF168-dependent ubiquitination signaling and disrupting DNA damage response signaling in autophagy-deficient cells." (PMID 38819674, 2024). "USP14 inhibits non-homologous DNA end joining (NHEJ) and increases cell death in response to IR in phosphatase and tensin homolog (PTEN)-deficient prostate cancer cells through targeting several NHEJ-associated proteins, including Ku70, Ku80, and ring finger protein 168 (RNF168)." (PMID 36552827, 2022).
ataxia telangiectasia (2 papers, 2016 to 2017). Ataxia-telangiectasia is the association of severe combined immunodeficiency (affecting mainly the humoral immune response) with progressive cerebellar ataxia. "By contrast with wild-type control and with ataxia–telangiectasia cells, we could not detect RNF168 protein in the LCLs from both patients." (PMID 29255463, 2017).
B-cell lymphomas (2 papers, 2011 to 2013).
cervical cancer (2 papers, 2015 to 2025). A primary or metastatic malignant neoplasm involving the cervix. "RNF168 is highly expressed in HPV+ cervical cancer and HNSCC HPV E7 limits the function of RNF168 at DSBs, favouring DNA repair by homology-directed recombination repair (HDR)." (PMID 40011575, 2025). "Finally, RNF8/RNF168 amplification is frequently found in human tumors and RNF168 gain of function was connected with human papillomavirus (HPV)-positive cervical cancers." (PMID 26442100, 2015).
colon cancer (2 papers, 2023 to 2025). "In colon cancer, research indicated that SENP1 diminished the phase separation of RNF168, thereby enhancing DNA damage repair and contributing to drug resistance." (PMID 41567198, 2025).
glioblastoma (2 papers, 2023). The most malignant astrocytic tumor (WHO grade IV). "A previous report demonstrated that RNF168 expression is suppressed in methylthioadenosine phosphorylase (MTAP)-deficient glioblastoma cells." (PMID 36771081, 2023). "Mechanistically, suppression of protein arginine methyltransferase 5 (PRMT5) attenuates the expression of RNF168 in methylthioadenosine phosphorylase (MTAP)-deficient glioblastoma cells, contributing to the destabilization of H2AX by SMURF2." (PMID 36694209, 2023). "In summary, an increasing number of studies about RNF168 indicate that it might be a new target for glioblastoma treatment." (PMID 36771081, 2023). "RNF168 also interacts with another E3 ubiquitin ligase, SMURF2, to modulate the stability of H2AX in glioblastoma cells." (PMID 36694209, 2023).
lung adenocarcinoma (2 papers, 2016 to 2022). A carcinoma that arises from the lung and is characterized by the presence of malignant glandular epithelial cells. "RNF168, a E3 ubiquitin ligase, is downregulated in lung adenocarcinoma, but upregulated in squamous cell carcinoma; the overexpression of RNF168 could inhibit the CSC features (such as sphere-formation ability, stemness markers ALDH) of NSCLC cells." (PMID 36033435, 2022).
microcephaly (2 papers, 2017 to 2021). A congenital or acquired developmental disorder in which the circumference of the head is smaller than normal for the person's age and sex. "From this comparison, it becomes evident that RNF168 deficiency is consistently associated with immunoglobulin deficiency and cellular radiosensitivity, whereas ataxia, microcephaly, short stature, or learning difficulties were more variable phenotypes and not found in each of the four patients." (PMID 29255463, 2017). "Several other DNA damage response proteins, which are binding partners of BRCA1 (such as SLX4, TOP3A, RNF168, and MCPH1) are also associated with microcephaly." (PMID 33441416, 2021). "Among them, two groups of excitatory neurons, THEMIS-PLA2G7 and FEZF2-SCN7A, express several PSGs involved in DNA damage response and mutated in patients with microcephaly such as BRCA1, NHEJ1, RNF168, and TOP3A." (PMID 33441416, 2021). "Among those, a number of DNA damage response genes associated with microcephaly in humans such as BRCA1, NHEJ1, TOP3A, and RNF168 show strong signs of positive selection and might have played a role in human brain size expansion during primate evolution." (PMID 33441416, 2021).
oesophageal cancer (2 papers, 2019 to 2022). "Depletion RNF168 causes decreased cell proliferation and invasion in oesophageal cancer cells." (PMID 30506884, 2019). "To investigate the function of RNF168 in oesophageal cancer cells in an unbiased approach, we carry out the whole genomic profiling based RNA sequence by comparison between control and RNF168 depletion in NEC cells." (PMID 30506884, 2019). "The current study reveals the function of RNF168 in promoting JAK‐STAT signalling in oesophageal cancer progression." (PMID 30506884, 2019). "Depletion of RNF168 significantly hampers the proliferation and invasion capacity in oesophageal cancer cells." (PMID 30506884, 2019). "In the study, we show that the E3 ubiquitin ligase RNF168 promotes oesophageal cancer cell proliferation and invasion, possibly via activating JAK‐STAT signalling." (PMID 30506884, 2019). "RNF168 gene is amplified in oesophageal cancer samples, which tends to correlate with poor prognosis." (PMID 30506884, 2019). "Here, we report an important function for RNF168 protein in supporting oesophageal cancer growth and invasion by stabilizing STAT1 protein." (PMID 30506884, 2019). "In parallel, the wound‐healing assay shows RNF168 depletion significantly decreases oesophageal cancer cell migration capability." (PMID 30506884, 2019). "Our study provides a novel mechanism that RNF168 promoting JAK‐STAT signalling in supporting oesophageal cancer progression." (PMID 30506884, 2019). "In order to investigate RNF168 function in oesophageal cancer, we deplete RNF168 expression by two individual siRNAs." (PMID 30506884, 2019). "The TCGA data (The Cancer Genome Atlas) shows that RNF168 gene is amplified in 25% of oesophageal cancer samples." (PMID 30506884, 2019). "This study provides a novel mechanism that RNF168 modulates JAK‐STAT signalling via regulating STAT1 protein stability in oesophageal cancer." (PMID 30506884, 2019). "Through unbiased RNA sequencing in RNF168 depleted oesophageal cancer cell, we identifies JAK‐STAT pathway is dramatically decreased." (PMID 30506884, 2019). "Considering the oncogenic role of STAT1 in oesophageal cancer, the RNF168 may be a promising new therapeutic target for oesophageal cancer therapy." (PMID 36042206, 2022). "In all, our study reveals an important cancer regulation mechanism between RNF168 and JAK‐STAT signalling, which indicates modulation of RNF168 protein could be an approach in inhibiting oesophageal cancer progression." (PMID 30506884, 2019). "Besides, we also observe that RNF168 gene is amplified in 25% of oesophageal cancer patients and tends to relate with shorter overall survival time." (PMID 30506884, 2019). "Firstly, we identify the localization of RNF168 in oesophageal cancer cells." (PMID 30506884, 2019). "Interestingly, RNF168 (RING finger protein 168) shows a high frequency of gene amplification in oesophageal cancer from TCGA database." (PMID 30506884, 2019). "All these experiments indicate that RNF168 is essential for oesophageal cancer cell progression." (PMID 30506884, 2019). "Immuno‐precipitation shows that RNF168 associates with STAT1 in oesophageal cancer cells." (PMID 30506884, 2019).
anal carcinoma (1 paper, 2022). "Some methylation probes including cg01550828 and its corresponding gene RNF168 have been reported to be associated with human papilloma virus-related anal cancer." (PMID 36249027, 2022). "RNF168 has been selected as a candidate associated with HPV-related anal cancer, validating the efficacy and accuracy of our prediction." (PMID 36249027, 2022).